CXCL1 (C-X-C motif chemokine ligand 1)
Diseases named in the same sentence as CXCL1 in open-access papers (continued):
Sharing a sentence is not in itself a finding about the gene and the disease.
COVID-19 (continued). "In the BAL fluid of patients with COVID-19, significantly increased and extremely high levels of the cytokines IL-1β, IL-1RA, IL-17A, TNF-α, and G-CSF and the chemokines CCL7, CXCL1, CXCL8, CXCL11, and CXCL12α were found in comparison with BAL fluid of patients with influenza." (PMID 34793331, 2022). "We additionally found 4 potential targets (CCL20, CSF3, CXCL1, CXCL10) with 6 existing drugs that could be repurposed for the treatment of COVID-19." (PMID 34582497, 2021). "Although CXCL1 was not reported to be upregulated in COVID-19 patient sera, it was highlighted as a significant element of upregulated transcriptome of SARS-CoV-2 infected normal human bronchial epithelial cells." (PMID 34262555, 2021). "Consistently, in this study we found the expression of a large number of cytokines are significantly elevated in COVID-19 patients BALF samples compared to control, including pro-inflammatory cytokines CXCL1, CXCL2, CXCL6, CXCL8, CXCL10/IP-10, CCL2/MCP-1, CCL3/MIP-1A and CCL4/MIP1B." (PMID 32228226, 2020). "Specifically, increased levels of various chemokines [C-X-C motif chemokine 1 (CXCL1), CXCL5, CXCL6, CXCL11] and cytokines [interleukin-17A (IL-17A), cluster of differentiation 40 (CD40), IL-6] were observed in the MIS-C group compared to the pediatric COVID-19 group." (PMID 39457139, 2024). "Similarly, mRNA levels of NF-κB target genes, including IL1β and IL10, were significantly increased independently of the severity of COVID-19, and CXCL1 and cyclooxygenase 2 (COX2) mRNA expression was significantly higher in PBMCs from patients with severe and critical COVID-19." (PMID 37310504, 2023). "The 10- to 100-fold higher levels of the most potent human neutrophil-attracting chemokine, CXCL8, and the neutrophil-attracting chemokines CXCL1 and CXCL5 in the BAL fluid of COVID-19 versus influenza patients could explain the major neutrophil infiltration in the lungs." (PMID 34793331, 2022). "Also, we found 6 existing drugs against 4 potential anti-COVID-19 targets (CCL20, CSF3, CXCL1, CXCL10) that might have novel anti-COVID-19 indications." (PMID 34582497, 2021). "Concordantly, for downstream genes of AP-1, the expression levels of some chemokine genes (e.g., CCL2, CXCL1, CXCL2, and CXCL10) were downregulated, while the expression levels of immune negative regulation genes (e.g. BCL3, NFKBIA, SOCS3, and TNFAIP3) were upregulated during the COVID-19 recovery." (PMID 33361761, 2020). "For instance, IL1B, NFKB1, NLRP3, PYCARD, and CASP1 are listed in the COVID-19 Disease Map, while there are molecules absent from it, including CCL3, 3L1, 4L2, CXCL1, 2, 3, 5, 16, TNFAIP6, C15orf48, TMEM176A/B, NFE2, PADI4, RAB20, ETS2, PHLDA2, FOLR3, and HP." (PMID 37719701, 2023). "Importantly, our meta-analysis identified 4 potential novel targets (CCL20, CSF3, CXCL1, CXCL10) associated with COVID-19 pathogenesis, targeted by 6 existing drugs that have not been studied in clinical trials for treatment of COVID-19 and could be repurposed." (PMID 34582497, 2021). "We show that plasma CXCL2, CXCL10, CCL5, CD40 ligand, IL-10, and GM-CSF concentrations and ELF CXCL1, CXCL10, granzyme B, TRAIL, and EGF concentrations were found in greater concentrations in COVID-19 than in non-COVID-19 ARDS patients." (PMID 33138839, 2020). "Importantly, CXCL1 and CXCL8/IL-8 are not the only chemokines significant in the course of COVID-19." (PMID 36613652, 2022). "As notable difference, strong induction of neutrophil-recruiting chemokines targeting CXC chemokine receptor (CXCR) 2, such as CXCL1, CXCL3, CXCL6, and CXCL8, were found only in human basal and secretory cells with severe COVID-19 but were absent in moderately-ill Syrian hamsters." (PMID 34381043, 2021).
ovarian carcinoma (71 papers, 2012 to 2026). A malignant neoplasm originating from the surface ovarian epithelium. "The CD74, CXCL1, and IL-6 released from surrounding cancer-associated mesenchymal stromal cells (CA-MSCs) have been reported to increase cancer stem cells of ovarian cancers." (PMID 40507922, 2025). "Elevated levels of circulating CXCL4 + CCL20 + CXCL1 in combination can discriminate among ovarian cancer patients those who are predisposed to shorter progression-free survival and overall survival." (PMID 40507922, 2025). "Ovarian cancer cells also cause an increase in CXCL1 and CXCL8/IL-8 expression in omental human peritoneal mesothelial cells." (PMID 37108425, 2023). "Among these candidates, CXCL1 was predicted as a downstream gene of miR-27b-5p, owing to CXCL1 has been implicated in the malignant phenotypes of ovarian cancer." (PMID 32782028, 2020). "Elevated production of the cytokines CXCL8 and CXCL1 have been implicated in autocrine-based drug resistance in various tumor cell lines and in poor clinical outcome in ovarian cancer patients." (PMID 28915246, 2017). "High serum CXCL1 levels are associated with a worse prognosis for ovarian cancer patients." (PMID 37108425, 2023). "CXCL1 may play a significant role in the tumorigenesis and formation of ovarian cancer, as confirmed by studies on CXCL1 gene polymorphisms." (PMID 37108425, 2023). "Nonetheless, it has been demonstrated that ectopic expression of CXCR2 in T-cells from normal donors or tumor-associated lymphocytes from ovarian cancer patients can increase their migration towards recombinant IL-8 and autologous ascites that contains CXCL1 and CXCL8 (IL-8)." (PMID 31091832, 2019). "Subsequent work implicated CXCL1 in breast, bladder, colon, and ovarian cancer." (PMID 26618099, 2015). "In ovarian cancer, the involvement of CXCL1 in NF-κB-driven metastasis remains underexplored, but these findings suggest a potential role for CXCL1 in regulating macrophage-cancer cell interactions within the ovarian tumor microenvironment." (PMID 40330466, 2025). "Studies have reported that the presence of Snail in ovarian cancer contributes to immunosuppression by up-regulating CXCL1 and CXCL2 expression which promotes recruitment of myeloid-derived suppressor cells (MDSCs)." (PMID 38935747, 2024). "In one study, CXCL1 was identified as a target gene for miRNA-27b-5p, and CXCL1 impaired the inhibition effect of miR-27b-5p on ovarian carcinoma cells growth." (PMID 38536591, 2024). "The mortality of ovarian cancer is largely due to metastatic burden, and Snail, CXCL1/2 levels, and MDSCs were all correlated with poor survival of ovarian cancer patients." (PMID 38786066, 2024). "In a separate study, miR-203a-3p was reported to target CXCL1 at the mRNA level, leading to the inhibition of proliferation, migration/invasion, and angiogenesis in ovarian cancer cells." (PMID 38793064, 2024). "Adiponectin plays a pro-angiogenic role in ovarian cancer via stimulation of CXCL1 secretion from ovarian cancer cells, which promotes angiogenesis independently of VEGF." (PMID 37686525, 2023).
ovarian carcinoma (continued). "In ovarian cancer cells, CXCL1 expression is also increased by Snail, a transcription factor important in EMT." (PMID 37108425, 2023). "We found that exposing ovarian cancer cells to catecholamines induced the expression of CXCL1 and CXCL8 chemokines, which were shown to promote cancer cell progression in a dose-dependent manner." (PMID 37762405, 2023). "Snail recruit myeloid-derived suppressor cells by upregulating CXCL1/2 to promote ovarian cancer progression." (PMID 36798787, 2023). "CXCL1 expression in ovarian cancer cells was also found to be dependent on metastasis-associated gene 1 (MTA1), the expression of which is increased in ovarian tumors." (PMID 37108425, 2023). "This is associated with an increase in CCL20/LARC expression by CXCL1, indicating some change in the expression of secretory factors during ovarian cancer development, in which CXCL1 is crucial at its beginning and CCL20/LARC at later stages." (PMID 37108425, 2023). "In ovarian cancer, high levels of CXCL1 expression have been found to promote cancer progression by inducing cell proliferation, whereas CXCL9 has been shown to potentiate anti-tumor activity and drive a positive response to anti-PD-L1 therapy." (PMID 36969851, 2023). "miR-200c, a member of the miR-200 family, inhibits intratumoral angiogenesis in ovarian cancer by downregulating the expression of interleukin (IL)-8 and C-X-C motif chemokine ligand 1 (CXCL1)." (PMID 36499626, 2022). "In sorafenib-treated osteosarcoma and ovarian cancer, the expression of CXCL1 increased significantly." (PMID 33826043, 2021). "For instance, researchers found that tumor-suppressor miRNA-27b-5p regulated the growth and metastatic behaviors of ovarian carcinoma cells by targeting CXCL1." (PMID 33763130, 2021). "Altogether, miR-27b-5p exerts suppressive roles in ovarian cancer progression through decreasing CXCL1 expression." (PMID 32782028, 2020). "Altogether, these findings imply that miR-27b-5p regulates the level of CXCL1 in ovarian cancer cell." (PMID 32782028, 2020). "Mechanistically, miR-27b-5p repressed the tumor growth and metastatic behaviors of ovarian cancer cell possibly via suppressing CXCL1." (PMID 32782028, 2020). "Serum CXCL1 is a novel circulating tumor marker for the differential diagnosis between benign ovarian masses and ovarian cancer." (PMID 32782028, 2020). "Previous report has indicated that CXCL1 induces the proliferation of ovarian carcinoma cell through transactivation of epidermal growth factor receptor (EGFR)." (PMID 32782028, 2020). "We found that variant rs11547681 was associated with ovarian cancer and demonstrated the 5’UTR for the functions of CXCL1." (PMID 32326946, 2020). "Immunoblotting analysis and qRT-PCR assay verified that transfection of pc-CXCL1 rescued the expression of CXCL1 in ovarian cancer cell in the presence miR-27b-5p." (PMID 32782028, 2020). "This research revealed that miR-27b-5p restrained the progression of ovarian carcinoma possibly via targeting CXCL1." (PMID 32782028, 2020). "In the current study, restoring CXCL1 expression counteracted the suppressive effects of miR-27b-5p in ovarian cancer cell." (PMID 32782028, 2020). "To elucidate the correlation between miR-27b-5p and CXCL1, the level of CXCL1 in ovarian carcinoma tissue was measured, and we found that the mRNA level of CXCL1 was upregulated in ovarian carcinoma tissue when compared to in adjacent sample." (PMID 32782028, 2020). "Overexpression of GAB2 in ovarian cancer cells promotes tumour growth and angiogenesis by upregulating the expression of CXCL1, CXCL2 and CXCL8, which are IKKβ-dependent." (PMID 31895688, 2020). "In our study, we evaluated the possible roles of miR-27b-5p-CXCL1 axis in the aggressive ability of ovarian carcinoma cell." (PMID 32782028, 2020).
ovarian carcinoma (continued). "We also analyzed CXCL1 expression in tumor samples from the TCGA data sets curated in Cbioportal and show that CXCL1 expression is elevated in multiple cancer types especially in ovarian cancer." (PMID 33126568, 2020). "Then, several rescue experiments were carried out to ensure that CXCL1 is essential for the functions of miR-27b-5p in ovarian cancer." (PMID 32782028, 2020). "Further, the fractalkine receptor (CX3CR1) expressed by ovarian cancer cells has also been demonstrated to mediate ovarian cancer cell adhesion to mesothelium by interacting with its ligand CXCL1 present on the surface of mesothelial cells’ surface." (PMID 30909510, 2019). "Ovarian cancer patients show elevated serum CXCL1/2, which correlates with Snail expression, MDSC infiltration, and short overall survival." (PMID 29703902, 2018). "High expression of CXCR2 or its ligand CXCL1 leads to increased ovarian cancer proliferation, which is believed to be partly mediated by transactivation of EGFR signaling, and the suppression of CXCR2 leads to apoptosis." (PMID 29515768, 2018). "As in mouse MDSCs, MDSCs from human ovarian cancer ascitic fluid samples were attracted by CXCL1, CXCL2, and CXCL5, and a CXCR2 antagonist inhibited this migration." (PMID 29703902, 2018). "In summary, CXCR2-driven ovarian cancer progression directly upregulates its own ligands such as CXCL1 and CXCL2." (PMID 29515768, 2018). "Several other groups have also shown many chemokines and cytokines, including IL-6, COX-2, and CXCL1, to be involved in tumor-related inflammation in epithelial ovarian cancer." (PMID 30380628, 2018). "Ovarian cancer patients showed significant increases in both CXCL1 and CXCL2 compared to those in healthy donors." (PMID 29703902, 2018). "Serum CXCL1 and CXCL2 levels are elevated in ovarian cancer patients and are associated with intratumoral MDSC infiltration." (PMID 29703902, 2018). "The top distinctive genes for the proliferation metaprofile include, besides previously used markers, numerous genes related to malignancy and ovarian cancer progression, in particular cytokines and their receptors: CXCL1, IL1A, CXCL8, IL1B, IL1R1, and IL1R2." (PMID 29362714, 2017). "Overexpression of GAB2 upregulated the secretion of several chemokines from ovarian cancer cells, including CXCL1, CXCL2 and CXCL8." (PMID 26657155, 2016). "In contrast, EGFR contributed to an enhanced production of cancer chemokines such as IL-8 and CXCL-1 in ovarian cancer cells." (PMID 27708225, 2016). "We found that overexpression of GAB2 in ovarian cancer cells upregulated expression of multiple chemokines, including CXCL1, CXCL2 and CXCL8 that exhibited mitogenic and pro-angiogenic activities." (PMID 26657155, 2016). "Taken together, these findings suggest that overexpression of GAB2 in ovarian cancer cells promotes tumor growth and angiogenesis by upregulating expression of CXCL1, CXCL2 and CXCL8 that is IKKβ-dependent." (PMID 26657155, 2016). "Particularly, ovarian cancer cell lines express high levels of proinflammatory chemokines CXCL1-3 and CXCL8 as specific ligands for the chemokine receptor CXCR2." (PMID 27723802, 2016). "Suppression of GAB2 in all three ovarian cancer cell lines decreased the mRNA levels of CXCL1, CXCL2 and CXCL8." (PMID 26657155, 2016). "The human ovarian cancer cell lines (pre-spreading in vitro) showed dominant expression levels of CXCL1-3, 8 and CXCR4, while EOC (post-spreading in vivo) had higher levels of CCL20, CXCL17 and CXCR4." (PMID 27723802, 2016). "Chemokine signature of a panel of 29 human ovarian cancer cell lines showed dominant expression of CXCL1-3, 8 and CXCR4." (PMID 27723802, 2016). "In ovarian cancer cells, though, the CXCL1 gene expression was found to be regulated mainly by NFκB pathway, specifically by the p65 DNA binding." (PMID 25790431, 2015).
ovarian carcinoma (continued). "In summary, CXCR2 expressing ovarian cancer cells potentiated NF-κB activation via EGFR-transactivated Akt signaling to induce CXCL1/2 secretion as an autocrine or paracrine growth factor." (PMID 24376747, 2013). "Other investigators reported that a CXCL1-induced cell proliferation in ovarian cancer cells was related to transactivation of EGFR." (PMID 24376747, 2013). "We demonstrated here that CXCR2 transiently-transfected human (SKOV-3) ovarian cancer cells similarly increased CXCL1 promoter activities via a critical proximal κB site." (PMID 24376747, 2013). "Since it was shown that CXCL1 can induce proliferation in epithelial ovarian cancer cells by transactivation of EGFR, we compared EGFR transactivation in SKA and SKCXCR2 cells." (PMID 24376747, 2013). "In our previous study, ovarian cancer cell lines highly expressed CXCL1-3 and CXCL8 which all have a high affinity for CXCR2." (PMID 24376747, 2013). "Inflammatory reaction induces mainly proinflammatory chemokines such as CXCL1, 2 and 8 via NF-κB signaling in ovarian epithelial cancer cells." (PMID 23300534, 2012). "Ovarian cancer tissue expresses high levels of CXCL1; similarly, serum levels of CXCL1 are higher in ovarian cancer patients than controls." (PMID 23300534, 2012). "Notably, previous studies have shown that CXCL1 promotes the proliferation of ovarian cancer cells via EGFR activation and mediates adiponectin-induced angiogenesis." (PMID 41360767, 2025). "Blocking CXCL1 or its downstream NF-κB activation may provide a novel therapeutic avenue for limiting ovarian cancer metastasis." (PMID 40330466, 2025). "The overexpression of CXCL1 has been shown to increase the proliferation of ovarian cancer cells." (PMID 41279931, 2025). "In addition, high expression of AFT3 and CXCL1 showed worse prognosis in ovarian cancer, while IGFBP7 behaved as a protective predictor according to multivariable analysis." (PMID 38395907, 2024). "Blood levels of CXCL1 in ovarian cancer patients are higher than in healthy individuals." (PMID 37108425, 2023). "Importantly, the increase in CXCL1 expression by either EGF or TNF-α depends on the lineage of the ovarian cancer." (PMID 37108425, 2023). "The enhancement of ovarian cancer cell proliferation by CXCL1 may occur through EGFR transactivation." (PMID 37108425, 2023). "CXCL1 levels in cyst fluid in ovarian cancer patients are higher than in serum." (PMID 37108425, 2023). "By activating CXCR2, CXCL1 increases the proliferation of ovarian cancer cells." (PMID 37108425, 2023). "For this reason, CAF show CXCL1 expression in the ovarian cancer niche." (PMID 37108425, 2023). "Additionally, in ovarian cancer (OC) patients, circulating CXCL1, CCL4, and CCL20 are elevated in serum specimens, which are associated with shorter recurrence-free survival (RFS) and OS." (PMID 36612163, 2022). "The authors identified that miR-27b-5p was significantly downregulated in ovarian cancer cases, and that it may have a role in the development and progression of ovarian cancer, potentially by targeting the CXCL1 gene." (PMID 36360295, 2022). "However, according to the literature data, elevated CXCL1 levels were found in patients with ovarian cancer, among others." (PMID 36431173, 2022). "Moreover, MDSC have been shown to be recruited into the ovarian cancer TME through the CXCL1/2–CXCR2 or CXCL12–CXCR4 axis." (PMID 33562495, 2021). "Finally, miR-27b-5p inhibited ovarian carcinoma cell growth in vivo and decreased the expression of CXCL1 in tumor tissue." (PMID 32782028, 2020).